HMGB1 (high mobility group box 1)
Diseases named in the same sentence as HMGB1 in open-access papers (continued):
Sharing a sentence is not in itself a finding about the gene and the disease.
tumor (continued). "A non-significant (p = 0.053) 1.6-fold increase of the HMGB1 level, as measured by immunohistochemistry, was detected 2 days after US+CA treatment compared to untreated tumours." (PMID 37631324, 2023). "In addition, HMGB1 promotes the release of IL-6 and IL-8 by activating MAPK- and MyD88-dependent NF-κB pathways, resulting in promoted tumor proliferation, angiogenesis, EMT, invasion and metastasis." (PMID 35493517, 2022). "Although NETosis was not addressed in this study, blocking HMGB1 function in tumor cells was effective to inhibit tumor metastasis." (PMID 35574410, 2022). "From patients with tumor RNA-seq data and an additional validation set of 38 unpaired ESCC samples, we further confirmed that HMGB1 mRNA expression was frequently upregulated in tumor tissues compared to the non-tumor counterpart (respectively)." (PMID 34617194, 2022). "The changes in CRT, HMGB1, HSP70, and ATP levels after BSA-FITC-Man@Mn2+-Ft@Lap treatment are immediate evidence for the ICD-inducing ability of the nanoassembly on 4T1 tumor cells, which would constitute a major source of tumor-derived dsDNA according to previous insights." (PMID 36167857, 2022). "Moreover, the protein levels of these three genes were detected using the human protein atlas (HPA) database, and the result showed the significant higher expression of CHMP4A, HMGB1 and PLK1 in the tumor tissues than in the normal ones." (PMID 36267972, 2022). "Exosomal HMGB1 enhanced DDR in recipient cells and made tumor cells more resistant to radiotherapy." (PMID 36335371, 2022). "For example, using these mouse models, it has been shown that macrophages regulate the cancer progression and formation of a high-density vessel network, and the high mobility group box-1 (HMGB-1) proteins play roles in promoting angiogenesis and tumor migration." (PMID 35629230, 2022). "At 3 days post-BPA-based BNCT irradiation in a SAS xenograft mouse model, plasma HMGB1 levels were higher than those in the non-irradiation control, and HMGB1 was detected in both nuclei and cytoplasm in tumor cells." (PMID 35336794, 2022). "On the other hand, in cSCC non-RDEB, HMGB1 overexpression in immunohistochemistry seems to be correlated to tumor progression, owing to the close link between this mediator and the tumor’s invasive and metastatic potential." (PMID 35207500, 2022). "During ICD induction, CRT, ATP, HMGB1, and other DAMPs are released in large quantities, stimulating the activation of ICD-related signaling pathways, triggering the endoplasmic reticulum stress response, and promoting the onset of ICD response in tumor cells." (PMID 36466838, 2022). "HMGB1 is actively secreted by innate immune cells, including monocytes, macrophages, and polymorphonuclear neutrophils in response to either LPS or TNF-α stimulation, and is released from damaged and tumor cells." (PMID 36078108, 2022). "We found no angiogenic ability of HUVECs in the absence of B cells, suggesting that HMGB1 derived from ESCC cells alone was not sufficient to elicit tumor angiogenesis in vitro." (PMID 34617194, 2022). "Its main feature is that dying cells can secrete DAMPs, including HMGB1, CRT, ATP, and Type I IFN, which can enhance the antigen presentation capability of APCs, activate T cells, and enhance the immunogenicity of tumor cells, ultimately trigger the arise of ICD." (PMID 36619616, 2022). "As a DAMP, HMGB1 is passively secreted into external environment from PDT-induced ICD tumor cells, while the mechanism of this process was not fully understood." (PMID 36329529, 2022). "Therefore, we aimed to investigate HMGB1 as a biomarker for BNCT response, by examining the early responses of tumor cells to 10B-boronophenylalanine (BPA)-based BNCT in the Kyoto University Nuclear Reactor." (PMID 35336794, 2022).
tumor (continued). "In addition, several soluble DAMPs, including HMGB1, ATP and HSP70, are released from tumor cells in a state of late apoptosis to send “find-me” signals, leading to DC maturation for the cross-presentation of tumor-associated antigens to T cells 9,24,25." (PMID 36258234, 2022). "More strikingly, we showed that adoptive transfer of macrophages that were pre-conditioned with HMGB1-depleted LCM yielded much smaller tumors than those pre-treated with HMGB1-sufficient LCM, highlighting the significance of tumor-derived HMGB1 in promoting the generation of pro-tumor macrophages." (PMID 36542153, 2022). "The damage-associated molecular patterns (DAMPs) were detected, which included high-mobility group box 1 protein (HMGB1), calmodulin (CRT) and heat shock protein 70 (HSP70), the release of which is commonly considered to be the signature of ICD occurrence in tumor cells." (PMID 36550159, 2022). "Metformin mitigated tumor growth in HFD-fed mice, paralleled by reductions in circulating glucose, insulin, soluble P-selectin, TGF-β1 and High Mobility Group Box-1 (HMGB1), as well as tumor expression of cell proliferation, aerobic glycolysis, glutaminolysis, platelets and neutrophils molecules." (PMID 36012397, 2022). "HMGB1, which is passively released by dying cells during ICD, binds to Toll-like receptor 4 (TLR4) on DCs, resulting in the efficient cross-presentation of antigens from the dying tumor cells." (PMID 36497086, 2022). "In ex-vivo cultured TRAMP tumour, treatment with rfhSP-D, with or without sivelestat, induced a robust HMGB1 release in the culture medium, suggesting an enhanced ICD." (PMID 35874783, 2022). "Tumor cells can induce ICD by expos to calreticulin (CRT) and releasing high mobility group protein B1 (HMGB1), this promotes the recruitment of antigen presenting cells (APCs) and tumor infiltration of T cells, which contribute to the activation of antitumor immune responses." (PMID 36338964, 2022). "Knockdown of tumor cell HMGB1 by shRNA did not inhibit tumor cell growth, whereas CD8+ T cell sensitized by tumor-specific IFN-g and TNF-a can be activated with attenuated functional Tregs." (PMID 36003395, 2022). "The immunoglobulin ELISA, flow cytometric, and immunohistochemical analyses indicated that B cells co-cultivated with HMGB1-overexpressing tumor cells did not exhibit characteristics of class-switched and/or antibody-secreting phenotypes." (PMID 34617194, 2022). "Moreover, the results of the immune checkpoint analysis showed that NOL7 expression in most tumor tissues was positively correlated with C10orf54, CD276, IL12A, and especially HMGB1." (PMID 36077008, 2022). "We also found that cancer-derived HMGB1 alone has no impact on tube formation or migration, further emphasizing the relevance of B cells in the control of tumor angiogenesis." (PMID 34617194, 2022). "Moreover, BoxA, a fragment of HMGB1 that corresponds to its first HMG domain, can also bind to CXCR4 and promote CXCR4-CD47 co-internalization and tumor cell phagocytosis." (PMID 35565443, 2022). "In the non-irradiated control, there was an increase in HMGB1 levels on day 8 compared to day 3, accompanied by tumor growth, which is consistent with our observation of the extracellular HMGB1 release from untreated SAS cells." (PMID 35336794, 2022). "Furthermore, the levels of DNA repair proteins (HMGB1, LIG, and XRCC1) and DNA excision repair protein (ERCC-3, a tumor-preventing gene) were detected by western blotting." (PMID 35473479, 2022). "Following the treatment with PC7A-ss-DOX, CRT exposure, as well as the release of adenosine triphosphate (ATP) and HMGB1 from B16-OVA cells, could be clearly detected, indicating that DOX released from PC7A-ss-DOX can effectively induce tumor ICD." (PMID 34983555, 2022).
tumor (continued). "Other TIM-3 ligands include the phospholipid PtdSer expressed on apoptotic cells, the alarmin high mobility group box 1 (HMGB1) that binds to DNA released from dying cells and the glycolipid CEA cell adhesion molecule 1 (CEACAM1) known to be highly expressed on tumour cells." (PMID 35595321, 2022). "The combination of cisplatin and 5-fluorouracil also induced a significant release of HMGB1, DC maturation/activation, upregulation of CD80 and CD86 in tumor cell ICD response, and further enhancement of the host antitumor immune response with a favorable prognosis." (PMID 36466838, 2022). "There are three tumours (DLBC, PAAD and THYM) with the higher mRNA expression levels of HMGB1." (PMID 35765707, 2022). "Three tumours (DLBC, PAAD and THYM) presented significantly elevated HMGB1 expression." (PMID 35765707, 2022). "Extracellular expression of HMGB1 and CRT was evaluated in the culture medium of tumour explant." (PMID 35874783, 2022). "Such HDAC‐dependent mechanisms controlling the localization of HMGB1 operate in normal cells including macrophage and hepatocytes, this appears not to represent an exclusive tumor adaptative mechanism." (PMID 36047643, 2022). "The pathway of ICD-induced tumour cell death relies on damage-associated molecular patterns (DAMPs) such as heat shock proteins (HSPs), high mobility group box 1 (HMGB1) and calreticulin (CRT), making tumour cells a “therapeutic vaccine” that can induce anti-tumour immunity." (PMID 36159787, 2022). "V937 treatment led to higher level of high mobility group box 1 (HMGB1) in the urine samples and cytosolic localization of the HMGB1 in the tumor tissues than the paired untreated NMIBC patient samples, suggesting V937-mediated induction of immunogenic cell death." (PMID 36091031, 2022). "In addition, peptides derived from the COOH-terminal motif of HMGB1 were also found to bind RAGE, inhibit the interaction between RAGE and HMGB1, and effectively suppress the pulmonary metastasis and invasion of tumor cells." (PMID 35956875, 2022). "Intracellular HMGB1 may act as a tumor suppressor in the initial stages of PDAC, while extracellular HMGB1 can promote inflammation and metastasis." (PMID 35884400, 2022). "Interestingly, for respiratory system‐related tumours, such as LUAD, LUSC and THYM, the DNA methylation levels of HMGB1 were all decreased." (PMID 35765707, 2022). "Our protein library contained 17 proteins in the context of an infection (CMV, HPV, EBV, HBV, mumps, LPS), tumor and cellular stress response (HSP27, HMGB1, CRT, HO-1, HO-2, IL8), autoimmunity (insulin, collagen, vimentin, albumin) or others (ovalbumin, bovine serum albumin)." (PMID 36429087, 2022). "HMGB1 was mainly detected in the nuclei of the tumor cells, nontumor epithelial cells, and inflammatory cells." (PMID 35280439, 2022). "HMGB1 plays a vital role in ICD and inducing an anti-tumor immune response." (PMID 33968889, 2021). "NET overproduction was also involved in promoting tumor cells proliferation, but also migration and invasion, favoring the crosstalk between glioma cells and the TME by regulating the HMGB1/RAGE/IL-8 axis or by activating pancreatic tumor growth through the DNA releases from NET." (PMID 33418996, 2021). "On the other hand, HMGB1 interacts with TLR2 on glioma cells to promote GSCs development and tumor progression via Wnt/β-catenin signaling, while their activation on DCs was shown to stimulate DC infiltration through activation of NF-κB, resulting in tumor suppression." (PMID 34715891, 2021). "Although the anticancer agent-induced release of these DAMPs is associated with the induction of antitumor immunity, research has shown that DAMPs such as HMGB1, CRT, and ATP are also involved in tumor progression, metastasis, and drug resistance, thereby representing a double-edged sword." (PMID 34638242, 2021).
tumor (continued). "Moreover, gastric cancer cell-derived exosomes that contain HMGB1, activate the TLR4/NFκB pathway in the neutrophils, resulting in increased autophagy and induction of the pro-tumor activity." (PMID 34572138, 2021). "Ferroptotic cancer cells can release and activate distinct signals including DAMPs (e.g., HMGB1, KRAS-G12D, and 8-OHG) or oxidized lipid mediators (e.g., 4HNE, oxPLs, LTB4, LTC4, LTD4, and PGE2) that may modulate inflammatory and anti-tumor immunity." (PMID 34796174, 2021). "Furthermore, EP treatment significantly decreased the release of HMGB1 from DLBCL cells, thus inhibiting tumor cell proliferation in vitro." (PMID 34599143, 2021). "HMGB1 is the main ligand of RAGE and could be released by tumor cell death after local liver therapy can lead." (PMID 34583662, 2021). "Furthermore, there was a negative correlation between the expression levels of miR-665 and HMGB1, and a positive correlation between the expression levels of lncRNA NHEG1 and HMGB1 in NB tumor sample." (PMID 34889712, 2021). "First step, dying tumor cells release tumor antigens such as CRT, HSPs, HMGB1 and ATP." (PMID 34123821, 2021). "The essential marker, CRT and HMGB1 were both overexpressed in MDA-MB-231 or 4T1 cell lines, which stimulates the recognition and phagocytosis of antigen-presenting cells (APCs) to dying tumor cells." (PMID 33866918, 2021). "Next, the YAP over-expression U87 GFP-Luci cells with or without HMGB1 down-regulation were injected into the right striatum of athymic nude mice to establish intracranial glioma and tumor growth was monitored every 7 days using bioluminescence values." (PMID 33726796, 2021). "No obvious inflammation, cell death, or tumor was detected in normal or FTLD model mice receiving administration of anti-HMGB1 antibody." (PMID 34385591, 2021). "To examine the role of HMGB1 in vivo, we established subcutaneous GBM xenograft models with patient-derived GBM cells, and observed the effect of glycyrrhizin, a HMGB1 inhibitor, on tumor growth." (PMID 33614649, 2021). "At each depth, expression levels of representative biomarkers of cellular apoptosis (caspase-3, termed as Cas-3), ICD (high mobility group box 1 protein, termed as HMGB1), and DC maturation (CD80 and CD86) were examined by immunofluorescent staining of tumor sections." (PMID 33531498, 2021). "Although the tumor stage has a major influence on OS, the prognostic value of HMGB1 has not been analyzed within these tumor stage subgroups." (PMID 33920544, 2021). "Exposure of the tumor cell supernatants to (toll-like receptor) TLR-2 or TLR-4 (principal receptors of HMGB1) reporter cells, however, did not induce a positive signal in these cells." (PMID 34876407, 2021). "Interactions between RAGE and S100 proteins or HMGB1 are involved in melanoma progression and metastasis, and the AGE/RAGE pathway was found to increase the phosphorylation of ERK and promote tumor progression, invasion, and metastasis in gastric cancer via the RAGE/ERK/Sp1/MMP2 pathway." (PMID 34199060, 2021). "However, TMA cores with higher Tumor Node Metastasis (TNM) staging and American Joint Committee on Cancer (AJCC) staging, as well as higher tumor grades, had higher HMGB1 cytoplasm-staining score and HMGB1 total score (p < 0.05)." (PMID 34257571, 2021). "In tumours, the status of several autophagy proteins, such as LC3b, ATG5, Beclin1 and its interacting proteins high mobility group Box 1 (HMGB1) and the Bcl-2-family, mostly assessed using immunohistochemistry, has been evaluated as a marker in several tumour types." (PMID 32929194, 2021). "The absence of HMGB1 expression in dying tumor cells compromises DC-dependent T-cell priming by tumor-associated antigens." (PMID 33815361, 2021). "HMGB1 is a ubiquitous non-histone chromosomal protein that is enriched in activated chromatin and plays tumor-promoting and antitumor roles in tumorigenesis." (PMID 34638242, 2021).
tumor (continued). "However, impaired tumor cells can generate DAMPs (such as calreticulin (CRT), high‐mobility group box 1 (HMGB1), and adenosine triphosphate (ATP)) by PDT‐induced immunogenic cell death." (PMID 33898169, 2021). "In vivo, EP could prevent the tumor growth and extend the survival of large B-cell lymphoma (DLBCL) mice model by downregulating the expression of HMGB1 and phosphorylation of ERK1/2 and Src." (PMID 34599143, 2021). "In addition, HMGB1 exerts autocrine or paracrine effects that activate DRP1 and lead to tumor recurrence." (PMID 33807275, 2021). "The release of high mobility group protein B1 (HMGB1) was demonstrated to drive IL-10 production in TAMs selectively through the receptor for advanced glycation end products (RAGE), leading to an IL-10-rich milieu within the tumor." (PMID 34603327, 2021). "On the side of the tumor cells, Nano-DOX is found to induce RAGE expression at the same time of stimulating HMGB1 secretion in the NSCLC cells, thus reinforcing PD-L1 upregulation by the autocrine HMGB1 as well as paracrine HMGB1 derived from the TAM." (PMID 34488792, 2021). "The present study indicates that the activation of nuclear and/or cytoplasmic HMGB1 could affect the stage of the tumor in CS-CCA, suggesting a prognostic tumor marker with the role of an inflammatory indicator." (PMID 35201494, 2021). "TIM-3 can also prevent innate immune activation by inhibiting the binding of HMGB1 to nucleic acids released from dying tumor cells; therefore, it has a negative role in antitumor response." (PMID 34572263, 2021). "Interaction of RAGE and HMGB1 leads to the phosphorylation of MAPKs and activation of the NF-κB signaling pathway in macrophages, which stimulates the release of pro-inflammatory cytokines (e.g., TNF-α and IL-1) by macrophages to promote tumor progression." (PMID 34796174, 2021). "The interactions between HMGB1 and TLR-2, TLR-4, and TLR-9 could also participate in cross-presentation of anti-tumor T lymphocytes in vivo, which lead to the activation of DCs and trigger antitumor immune responses." (PMID 35069604, 2021). "HMGB-1 functions as a crucial DAMP showing immune-stimulatory and pro-inflammatory effects Lastly, extracellular adenosine triphosphate (ATP), released from dying tumor cell expresses a “find me” signal." (PMID 34452256, 2021). "In their study, interaction between HMGB1 and TIM‐3 on DC interfered with nucleic acid recruitment to endosomal compartments and impaired innate immune sensing of nucleic acids released from dying tumor cells." (PMID 32508018, 2020). "Furthermore, the released HMGB1 stimulates the synthesis of pro-inflammatory factors, APC maturation, and presentation of tumor antigens by TLR439." (PMID 33299118, 2020). "Free OLE enters tumour cells and induces ICD through the released HMGB1 from the dying cells." (PMID 33009382, 2020). "Moreover, they investigated tumor tissues of 50 CRC patients and found HMGB1 and RAGE protein coexpression in 65.6% of trophinin-positive patients." (PMID 33117687, 2020). "Moreover, dying tumor cells also secreted HMGB1, VEGF, etc. to accelerate proliferation of the admixed surviving tumor cells, promote angiogenesis, and facilitate cancer cell repopulation and metastasis." (PMID 32228703, 2020). "These authors demonstrated that during hypoxia, HMGB1 translocates from the nucleus to the cytosol, where it binds to DNA released from damaged mitochondria, resulting in activation of intracellular TLR9 and tumor cell proliferation." (PMID 32664328, 2020). "Indeed, conditioned medium derived from LLC cells (LLC‐CM) or LLC tumour masses (LLC‐TM) contained significant amounts of S100B and HMGB1." (PMID 32159297, 2020). "Furthermore, we investigated the changes in the expression of multiple critical factors (including COX-2, TNF-α, β-catenin, HMGB1, PCNA, PPAR-γ, AP-2, Smad-2, TGF-β1) for the tumor microenvironment after treatment with nanoparticle-encapsulated LSW." (PMID 32754037, 2020).